PRL (prolactin)
Diseases named in the same sentence as PRL in open-access papers (continued):
Sharing a sentence is not in itself a finding about the gene and the disease.
COVID-19 (continued). "Next, they compared the profiles of pituitary hormone between the cohort of COVID-19 patients and healthy controls in this study, which is well matched in age and gender, and found significantly increased levels of serum PRL and ACTH in the COVID-19 group." (PMID 37550713, 2023). "In the present study, we identified high PRL/TLR3 and low PRL/TLR3 endotypes of COVID-19 patients in two heterogeneous cohorts using whole-blood samples of the patients at the time of admission to the ICU." (PMID 37966347, 2023). "In the present study, we identified two key RNAs (PRL and TLR3) associated with the prognosis of COVID-19." (PMID 37966347, 2023). "The main findings were: lower AMH levels, increased FSH levels, and higher testosterone and prolactin levels in women in the COVID-19 group, compared to the age-matched control group." (PMID 35055804, 2022). "This signifies the level of Prolactin was about 3 ng/ml times more among those recovered from COVID-19." (PMID 34876801, 2021). "COVID-19 patients have shown interestingly higher levels of LDH, leukocytosis, CRP, and prolactin, which have been considered to be pivotal factors for ocular manifestations of COVID-19." (PMID 34595136, 2021). "Regarding the hormones, statistically significant higher LH and prolactin were found among those COVID-19 patients." (PMID 34876801, 2021). "Elevated levels of blood prolactin were observed in patients diagnosed with active COVID-19." (PMID 38673504, 2024). "This study aimed to assess PRL as a biomarker for disease severity in COVID-19." (PMID 39595974, 2024). "While there was no initial correlation found between prolactin levels and sexual function, a long-term follow-up of COVID-19 patients indicated a significant relationship between higher prolactin levels and increased arousal and hydration, as measured by the FSFI." (PMID 38673504, 2024). "Therefore, the current study aimed to assess the menstrual disorder and the AMH, TSH, TPO, and prolactin levels in female patients with COVID-19." (PMID 39906086, 2024). "In COVID-19 high PRL levels might reflect an attempt by the body to counterbalance the excessive inflammation and support immune defense." (PMID 39595974, 2024). "Monitoring the baseline level of prolactin in male patients may help with the prognosis and clinical management of COVID-19 due to the high concentration of prolactin, which inhibits the HPG axis’ signaling." (PMID 38345682, 2024). "The relationship between prolactin and COVID-19 severity may also be affected by other factors such as age and patients’ underlying health conditions." (PMID 38673504, 2024). "For this reason, it was hypothesized that controlled augmentation of prolactin could provide protective benefits for patients infected with COVID-19." (PMID 37759668, 2023). "The results of experimental research proved that prolactin acts as an anti-inflammatory and immunomodulatory factor and thus may play an important role in limiting COVID-19 hyperinflammation." (PMID 37790604, 2023). "Finally, we found that in the group of COVID-19 survivors, prolactin concentrations were significantly higher compared to the control group." (PMID 37790604, 2023). "The results of our study suggest the potential role of PRL as a pro-inflammatory agent in COVID-19." (PMID 37966347, 2023). "Our publication trend analysis revealed that among the 128 research articles, 38 studies assessed male reproductive hormones (such as testosterone, luteinizing hormone, follicle-stimulating hormone, prolactin, estradiol, and inhibin) in COVID-19 patients with reproductive issues." (PMID 37987419, 2023). "Therefore, we also analyzed the relationship between serum AMH/T/PRL and the immune and inflammatory characteristics of COVID-19 patients in order to determine the impacts of the corresponding “immune/inflammatory storm” on ovarian function." (PMID 33816526, 2021).
COVID-19 (continued). "Notably, the serum pituitary hormone LH and the PRL level were significantly elevated in COVID-19 patients, indicating a severe endocrine disorder." (PMID 33816526, 2021). "However, there were significant higher serum T (0.38/0.39 vs. 0.22 ng/ml, P < 0.001/ < 0.001) and PRL (25.43/24.10 vs. 12.12 ng/ml, P < 0.001/ < 0.001) levels in both basal and all-COVID-19 groups." (PMID 33816526, 2021). "Interestingly, our study suggests that zidovudine, which targets O’-methyl transferase (Nsp16) can also bind to prolactin and can be of high significance in management of COVID-19 due to dual ability to affect Nsp16 and prolactin." (PMID 33841751, 2021). "Our study indicates that severe acute respiratory syndrome coronavirus 2 (SARS-CoV-2) infection might have long-term consequences on the endocrine system, including the suppressed function of the thyroid gland, prolactin, and male sex hormone secretion." (PMID 37790604, 2023). "For further analysis, we compared the PRL and TLR3 in plasma of 54 COVID-19 patients and 20 healthy subjects." (PMID 37966347, 2023). "Studies have suggested elevated PRL in COVID-19 cases compared to non-infected patients; however, study heterogeneity is noted." (PMID 39595974, 2024). "Therefore, PRL and TLR3 were established as the two key RNAs related to the prognosis of COVID-19 patients." (PMID 37966347, 2023). "Prolactin levels were 27.86 ± 4.35 ng/L in vaccinated males, 5.35 ± 1.59 ng/L in non-vaccinated males, and 16.65 ± 6.15 ng/L in COVID-19 male patients." (PMID 37658087, 2023). "This study provides the initial clinical evidence showing that female COVID-19 patients probably have an ovarian injury, with a poor ovarian reserve of decreased AMH and reproductive endocrine disorder of aberrant sex hormone levels, especially high T and PRL." (PMID 33816526, 2021). "Prolactin level among those recovered from COVID-19 was more than that among non-COVID-19 groups with overall MD (95% CI) of 3.21 (1.71, 4.72) with presence of low heterogeneity (p = 0.21, I2 = 34.39%) from 3 studies." (PMID 34876801, 2021). "Our results indicate that although no obvious menstrual cycle change was observed, women affected by COVID-19 have a significantly lower serum AMH level and higher T/PRL level, suggesting a poor ovarian reserve and abnormal reproductive hormones compared to the age-matched healthy unaffected women." (PMID 33816526, 2021). "However, after one month, when patients became convalescent, their prolactin levels were comparable to the control group and remained stable during follow-up, regardless of the severity of their COVID-19 course." (PMID 38673504, 2024). "This complex interplay suggests that PRL may modulate the immune response in COVID-19 in a manner that is not directly captured by static measurements of IL-6 but which becomes apparent through dynamic changes over time and in the context of disease severity." (PMID 39595974, 2024). "Importantly, PRL has been shown to regulate the expression of cytokines such as IL-1β, IL-6, and TNF-α, which are key players in the inflammatory response observed in severe COVID-19 cases." (PMID 39595974, 2024). "According to analysis of the included studies, patients with COVID-19 had significantly low T/LH, FSH/LH, and SHBG levels and high levels of LH, and E2/T, but their levels of FT, FSH, PRL, E2, and progesterone were not affected." (PMID 36303865, 2022).
breast tumor (24 papers, 1979 to 2025). "PRL regulates breast tumor metastasis: PRL expression has been associated with cell invasion, metastasis and reduced survival." (PMID 38660565, 2024). "Experimental and epidemiologic data suggest that prolactin is associated with mammary gland development, and also the increased risk of breast tumors and metastatic disease in postmenopausal women." (PMID 27782069, 2016). "Higher levels of PRL in postmenopausal women may eventually lead to an increased risk of breast tumors and metastatic cancer." (PMID 36187116, 2022). "SOCS1 expression in breast tumor tissues and cell lines might be caused by proinflammatory cytokine, growth hormone, and prolactin in the tumor microenvironment, which result in the loss of sensitivity to subsequent prolactin stimulus." (PMID 28228755, 2017). "PRL exerts pleiotropic effects that extend beyond epithelial cells to critically modulate the breast tumor microenvironment." (PMID 41370498, 2025). "EGF released by the stromal microenvironment surrounding the breast tumor activates signaling cascades that overlap with PRLr signaling cascades upon activation with PRL secreted by breast tumor cells." (PMID 40160874, 2025). "Especially, ENPP2 was significantly correlated with “IL-6 cytokine receptor ligand interactions”, “LIF signaling 1 up”, “TGFβ receptor signaling” and “prolactin signaling pathway” in human breast tumors." (PMID 37296899, 2023). "Extracellular matrix components in the breast tumor microenvironment can also influence PRL/PRLR signaling." (PMID 36187116, 2022). "Excess PRL has also been shown to increase the frequency and rate of tumor growth in many rodent models of spontaneous and carcinogenically induced breast tumors." (PMID 34945164, 2021). "Elevated levels of PRLR in breast tumors, high circulating levels of PRL and increased expression of ERBB1/2 in patients that become resistant to endocrine therapy have shown to be associated with higher risk of cancer progression." (PMID 34572912, 2021). "PRL/PRLR signaling can also influence the breast tumor microenvironment through extracellular matrix components." (PMID 34572912, 2021). "In postmenopausal women with increased PRL and PRLR there is an increased risk of developing breast tumors and metastasis." (PMID 34572912, 2021). "Knowing from her own research that prolactin had been identified as a hormone with perhaps an even greater significance than estrogen in the maintenance of breast tissue and breast tumor growth, she started reading the relevant literature." (PMID 28955226, 2017). "During pregnancy and lactation, it is expected that women would experience transiently different gestational hormonal environments, such as increased estrogen, progesterone, prolactin, and growth hormone concentrations stimulating breast tumor cells." (PMID 25875532, 2015). "Prolactin (PRL), a polypeptide hormone of the growth hormone/cytokine family produced by lactotrophs in the anterior pituitary gland and in normal and breast tumors, exerts its diverse functions through specific transmembrane receptors." (PMID 25193864, 2014). "While additional studies are needed, this suggests that prolactin may act on human breast tumor development through alternative pathways." (PMID 36882838, 2023). "Prolactin, through its receptor, stimulates the proliferation of breast tumors and cancer cells." (PMID 25193864, 2014). "One hypothesis put forth to explain this prevalence is that the prolactin-rich environment of the pituitary enhances the proliferation of breast tumor cells." (PMID 22312541, 2012). "In addition, breast tumour cells have been shown to synthesise and secrete PRL in cell culture models." (PMID 20736944, 2010). "Our data would suggest that endogenous levels of prolactin in breast tumours may be indicative of the efficacy of current treatment regimens designed to eliminate cancer cells via modulation of endogenous ceramide production." (PMID 15213724, 2004).
breast tumor (continued). "Recent studies do not provide a clear picture of PRL’s role and its receptors in the differentiation, growth, and development of breast tumors." (PMID 34945164, 2021). "In addition, breast tumors with HER2 overexpression had higher proliferation and metastasis with the presence of prolactin stimulating tyrosine phosphorylation of HER2 and activating mitogen-activated protein kinase (MAPK) signaling." (PMID 25875532, 2015).
gestational diabetes (24 papers, 2016 to 2025). Carbohydrate intolerance first diagnosed during pregnancy. "A positive correlation was found between increases in PRL levels in early pregnancy and subsequent risk of gestational diabetes." (PMID 39763651, 2024). "Interestingly, high PRL level during pregnancy attenuates the development of postpartum T2D though reduced PRL level in pregnant women with gestational diabetes is regarded as a predictive risk factor for the development of T2D within 10 years." (PMID 39663784, 2024). "PRL is essential for regulation of pancreatic β cell function during pregnancy; therefore, reducing of PRL in women with gestational diabetes is linked with future pancreatic β cell dysfunction and development of T2D since PRL enhance insulin signalling and sensitivity." (PMID 39663784, 2024). "However, two studies have shown PRL that levels during pregnancy were associated with gestational diabetes mellitus risk and reduced tolerance glucose during pregnancy." (PMID 36704037, 2022). "However, other studies have demonstrated an opposite result: an inverse association between PRL and risk for gestational diabetes mellitus." (PMID 36704037, 2022). "These adaptations, mediated in part by hormones such as prolactin, ensure an adequate supply of nutrients to the developing fetus but also increase the risk of gestational diabetes mellitus (GDM)." (PMID 40244235, 2025). "Human in vitro islet studies demonstrated that beta cells replicate in response to prolactin (PRL), and the epidemiological study reported that PRLR SNPS are associated with gestational diabetes." (PMID 35204716, 2022). "Concerning cord blood prolactin, differences between gestational hypertension group and the other groups; uncomplicated pregnancy, gestational diabetes and preterm labour groups were all significant (P= 0.000, P= 0.006, P= 0.000 respectively)." (PMID 31372154, 2019). "Comparison of cord blood prolactin between uncomplicated pregnancy and Gestational hypertension, Gestational diabetes and Preterm labour." (PMID 31372154, 2019). "In this study, we found that cord prolactin is significantly higher in gestational diabetes group than the preterm labour group, whereas other studies observed a slightly higher cord prolactin level in preterm labour group, thus further research is needed to investigate these contradicting findings." (PMID 31372154, 2019). "In this study, maternal and cord blood prolactin were measured and comparison of cord blood prolactin between different groups (uncomplicated pregnancy, pregnancy with gestational hypertension, pregnancy with gestational diabetes and preterm labour) was done." (PMID 31372154, 2019). "The purpose of this study was to further evaluate the relationship of various protein markers, including prolactin, HGF, TNFα, TRAIL, PAI-1, RANKL, and OPG, with gestational diabetes in women." (PMID 30147996, 2018). "More broadly, prolactin action is considered essential for metabolic homeostasis during pregnancy and a lack of prolactin receptors resulted in gestational diabetes in animal models." (PMID 32180760, 2020). "Furthermore, PRL stimulates β-cell proliferation, survival, and insulin production and pregnant mice lacking PRL receptors in β-cells develop gestational diabetes." (PMID 33746901, 2021). "This is, to the best of our knowledge, the first study to evaluate the mediation effect of PRL on improvement in glucose metabolism and MIR in breastfeeding women with and without gestational diabetes." (PMID 37711904, 2023).
Primary hypothyroidism (24 papers, 2012 to 2024). A type of hypothyroidism that results from a defect in the thyroid gland. "Other causes of an elevated serum PRL level, with values below 250 ng/mL, include drugs, pregnancy, kidney failure, liver failure, polycystic ovary syndrome, and primary hypothyroidism." (PMID 39051300, 2024). "First, increased TRH caused by primary hypothyroidism can promote PRL secretion in lactotroph cells, usually with PRL values <100 μg/L." (PMID 33329389, 2020). "Primary hypothyroidism is associated with low GH levels and reversible pituitary hyperplasia in addition to abnormal thyroid function and PRL levels." (PMID 26421010, 2015). "Primary hypothyroidism causes health issues in various physiological systems, affecting the hypothalamus anterior‐pituitary axis, leading to abnormalities in growth hormone, adrenocorticotrophic hormone, prolactin, and gonadotropin production." (PMID 38268116, 2024). "In patients with primary hypothyroidism, the elimination rate of prolactin is usually lower, which augments the concentrations of prolactin in the blood." (PMID 35269847, 2022). "Median (25th–75th percentile) values for serum prolactin levels in euthyroid children, children with ScH, and those with overt primary hypothyroidism were 13.3 (9.4-17.95) ng/mL, 19.15 (15.97-30.12) ng/mL, and 28.86 (17.05-51.9) ng/mL, respectively (p<0.001)." (PMID 28529200, 2017). "Primary hypothyroidism leads to increased thyrotropin-releasing hormone (TRH) release from hypothalamus, which has a physiologic trophic effect on thyrotrophs and lactotrophs resulting in increased TSH and prolactin levels, respectively." (PMID 28529200, 2017). "The lack of thyroxine feedback found in uncontrolled primary hypothyroidism leads to elevated levels of TRH which causes both pituitary thyrotroph and lactotroph hypertrophy, increasing the secretion of both TSH and prolactin." (PMID 23133775, 2012).